CXCL12 (C-X-C motif chemokine ligand 12)
Diseases named in the same sentence as CXCL12 in open-access papers (continued):
Sharing a sentence is not in itself a finding about the gene and the disease.
gastric cancer (continued). "In summary, we show that GPCRs are differentially expressed in gastric cancer tissue and may contribute to the tumour biology: tumours expressing both, CXCL12 in tumour cells and CXCR4 in tumour surrounding microvessels, show a highly significant association with local tumour growth and UICC stages." (PMID 20386750, 2010). "For example, the chemotactic factor CXCL12 is known to promote the resistance of CRC 33 and gastric cancer 14 cells to 5-FU." (PMID 38817851, 2024). "In gastric cancer (GC), the high expression of CXCL12 by CAFs may influence the malignancy of tumor cells." (PMID 37173977, 2023). "Previous studies demonstrated that the CXCL12/CXCR4 axis plays an important role in the metastasis of many malignancies, including gastric cancer." (PMID 35877436, 2022). "Several other studies also proposed that the CXCL16/CXCR6 and the CXCL12/CXCR7 axes promoted the proliferation and migration of gastric cancer cell." (PMID 34831211, 2021). "Western blot analysis confirmed that knockdown of circDLG1 significantly decreased the protein level of CXCL12 in SGC7901 and HGC27 gastric cancer cells." (PMID 34911533, 2021). "The CXCL12/CXCR4 axis was claimed to promote macrophage polarization toward M2-like phenotypes, and thus, enhance gastric cancer metastasis." (PMID 34831211, 2021). "We found that DCLK1 expression significantly correlates with both TGFB1 and CXCL12 and their receptors TGFBR1, TGFBR2, and TGFBR3, and CXCR4, respectively, in colon and stomach cancer patients." (PMID 31979136, 2020). "In gastric cancers, IL6 activates fibroblastic Twist1, and the resulting CAFs secrete the chemokine CXCL12 in a Twist1‐dependent manner." (PMID 28544627, 2017). "Previous studies had been demonstrated that CXCL12/CXCR4 axis plays an important role in metastasis of many malignancies, including gastric cancer." (PMID 23936528, 2013). "The candidate genes CXCL12 and its receptor CXCR4 were validated by real-time reverse-transcription polymerase chain reaction in an independent set of 37 gastric carcinomas." (PMID 20386750, 2010). "The differential expression of CXCL12- and CXCR4-mRNA was validated by real-time RT-PCR in an independent set of 37 intestinal type gastric carcinoma samples." (PMID 20386750, 2010). "In addition, it has been reported that peritoneal metastasis in gastric cancer proves to be related to the interaction between VEGF, CXCR4, and CXCL12." (PMID 36131788, 2022). "Moreover, CXCL12 can induce epithelial-mesenchymal transition (EMT) and gastric cancer metastasis possibly through the interaction between MET proto-oncogene (c-MET) and CXCR4." (PMID 35265130, 2022). "The involvement of CXCL12/CXCR4 signaling in tumor invasion and metastasis was also confirmed in other several cancer types, including non-small cell lung cancer (NSCLC), gastric cancer (GC), and prostatic carcinoma (PCa), and also linked to the promotion of cancer stem cell proliferation." (PMID 32466591, 2020). "Although CXCL12 promotes the expression of Snail1 and Twist1 in glioblastoma cancer cells, and of Snail1 in human oral squamous cell carcinomas, no reports show CXCL12‐induced expression of Snail1 or Twist1 in tumour cells of gastric cancers." (PMID 28544627, 2017). "Regarding the mechanism of FMNP-labeled MSCs recognizing in vivo gastric cancer cells, we consider that CCL19/CCR7 and CXCL12/CXCR4 axis loops may be involved in this course." (PMID 22709686, 2012). "Concerning chemokine receptors and chemokines, the expression of the chemokines CCL2 and CXCL12 were increased in nodal positive gastric cancer compared to nodal negative cases." (PMID 20386750, 2010). "CXCL12 expression was significantly increased in gastric carcinoma compared with non-neoplastic mucosa (p = 0.033)." (PMID 20386750, 2010). "Confirming the array data, CXCL12 expression was also up-regulated in nodal positive gastric carcinoma compared with nodal negative cases." (PMID 20386750, 2010).
gastric cancer (continued). "Similarly, in gastric cancer, activation of the CXCL12/CXCR4 axis via the STAT3 pathway induces downregulation of E-Cadherin and upregulation of N-Cadherin, Vimentin, and Snail, enhancing EMT, migration, and the invasiveness of gastric cancer cells." (PMID 38920657, 2024). "However, the CXCL1/CXCL8-CXCR2 axis may also cooperate with other chemokines in gastric cancer cell migration, particularly C-X-C motif ligand 12 (CXCL12, stromal-derived factor-1 (SDF-1))-CXCR4." (PMID 37408240, 2023). "Therefore, the contribution of Cxcl12/Cxcr4 in antral stem cells and other form of gastric cancer has not been fully elucidated." (PMID 29340033, 2017). "Comparing our gene array data with those obtained by RT-PCR and immunohistochemistry, it was interesting to note that the differential expression of CXCL12 in node positive gastric carcinoma was confirmed on the transcriptional but not on the translational level." (PMID 20386750, 2010). "However, whether CXCR4/CXCL12 affected regorafenib sensitivity in gastric cancer cell has not been fully investigated." (PMID 28489887, 2017).
diabetes (80 papers, 2008 to 2026). "The presence of diabetes in rats or intravitreal injection of HMGB1 in normal rats significantly upregulates the levels of mRNAs encoding SDF-1/CXCL12 receptor CXCR4, as well as levels of HIF-1, EGR-1, TK-2, and CXCL12/CXCR4 proteins in the chemokine axis." (PMID 30473885, 2018). "As necrosis emerges as an important mechanism of β-cell loss in diabetes, we explored the beneficial effects of CXCL12 on necrotic β-cell death." (PMID 24988468, 2014). "In non-obese diabetic (NOD) mice, which are predisposed to develop the disease, reduction of CXCL12 level leads to significant delays in the onset of diabetes." (PMID 18793419, 2008). "The elevated CXCL12 expression is unlikely a consequence of inflammation or hyperglycemia associated with insulitis or diabetes in NOD mice because CXCL12 transcript was detected in the bone marrow of EA16 mice and young (4–5 week old) NOD mice." (PMID 18793419, 2008). "Furthermore, apart from influencing anticancer drug efficacy on diabetes-associated T cells, CXCL12 also mediates firm adhesion processes for normal T cells." (PMID 40001479, 2025). "Serum VEGF and CXCL-12 levels were measured by enzyme-linked immunosorbent assay (ELISA) at three stages (normal stage, diabetes mellitus [DM] stage, and DFU stage)." (PMID 41933922, 2026). "Transgenic mice expressing CXCL12 in their β-cells are protected against streptozotocin-induced diabetes through the activation of the pro-survival protein kinase Akt and downstream pro-survival, anti-apoptotic signaling pathways." (PMID 40799516, 2025). "An analysis of laboratory data from patients with type 2 diabetes mellitus (T2DM) revealed significant upregulation of CXCL12 expression, which contradicts the downregulation observed in T1DM beagle dogs described in this study." (PMID 40001479, 2025). "Blocking CXCR4 induces apoptosis and reduces cell survival markers in β-cells, while overexpressing CXCL12 in β-cells enhances resistance to apoptosis and diabetes." (PMID 39070795, 2024). "Analysis of tissues from mice at 2 months of diabetes duration revealed a sustained reduction in Cxcl12 expression in the tibia and femur, suggesting that these changes are also sustained over time, much like TGFB suppression." (PMID 36307522, 2022). "Although the role of CXCL12 in diabetes is complex, the CXCL12/CXCR4 axis in adipose tissue has been associated with the production of proinflammatory cytokines and, finally, systemic insulin resistance." (PMID 35740314, 2022). "Since our studies identified suppressed TGFB signaling in diabetes, we examined if stem cell niche factors, including CXCL12, were affected." (PMID 36307522, 2022). "It has been reported that CXCL12 is highly induced in some pro-atherogenic pathological conditions such as hyperlipidemia and diabetes." (PMID 33119719, 2020). "In contrast, HSCs in type 1 and 2 mouse models of diabetes are unable to mobilize HSCs in response to G-CSF as CXCL12 expression is abnormally maintained in MSC niche cells." (PMID 32823583, 2020). "The function of CXCL12 as a proangiogenic factor together with its ability to recruit endothelial progenitor cells accelerates wound healing in diabetes." (PMID 31507535, 2019). "A trio of genes encoding angiogenic factors—FGF2, CXCL12 and LEP—were downregulated by diabetes (FGF2 an CXCL12, p < 0.01 vs control group; LEP, p < 0.05 vs control group)." (PMID 31001672, 2019). "Current research has positioned CXCL12 as an important molecule in potential treatment of diabetes and its complications." (PMID 26300887, 2015). "Several reports have revealed that neutralization of CXCL12 inhibits insulitis and diabetes development." (PMID 26300887, 2015). "Transgenic mice overexpressing CXCL12 in β-cells are protected from streptozotocin (STZ)-induced diabetes via activation of Akt kinase." (PMID 26300887, 2015). "A complete understanding of the complex CXCL12 network is a prerequisite for the safe application of CXCL12-based therapy in diabetes." (PMID 26300887, 2015).
diabetes (continued). "Considering the involvement of CXCL12 in β-cell differentiation, growth, and survival, an understanding of CXCL12 transcriptional regulation offers possibility to improve β-cell mass in diabetes." (PMID 26300887, 2015). "Since diabetes is accompanied by dysfunction and life-threatening damage of several organs, the potential of CXCL12 to create a microenvironment that supports repair processes is particularly important." (PMID 26300887, 2015). "Diabetes-related studies have provided evidence for an important role of CXCL12 in anti-apoptotic and anti-necrotic protection of β-cells from diabetogenic agents." (PMID 26300887, 2015). "The role of CXCL12 in diabetes promotion and progression remains elusive due to its multiple functions and the overwhelming complexity of diabetes." (PMID 26300887, 2015). "We believe that the antinecrotic effect of CXCL12 is particularly important in diabetes as it prevents the generation of an additional pro-inflammatory burden resulting from β-cells proceeding along the necrotic pathway." (PMID 24988468, 2014). "Transgenic mice that overexpress CXCL12 in their beta cells are resistant to apoptosis and diabetes." (PMID 23555743, 2013). "WP supplementation in the diabetes model was found to significantly increase CXCL12- and CCL21-mediated actin polymerization and chemotaxis in both B and T cells." (PMID 22070978, 2011). "Together, these findings strongly suggest that CXCL12 promotes development of diabetes in NOD mice and perhaps in humans." (PMID 18793419, 2008). "In NOD mice, neutralization of CXCL12 by administration of antibody suppresses insulitis and delays the onset of diabetes." (PMID 18793419, 2008). "In support of this notion, systemic administration of CXCL12 ameliorates diabetes, perhaps partly by mobilizing HSC from the bone marrow to the periphery." (PMID 18793419, 2008). "In NOD mice, the onset of diabetes is significantly delayed by reducing the level of CXCL12 either by antibody-mediated neutralization or G-CSF-induced suppression of CXCL12 transcription." (PMID 18793419, 2008). "Complete Freund adjuvant (CFA), which is known to inhibit diabetes development, also inhibits CXCL12 expression and T cell accumulation in the bone marrow of NOD mice." (PMID 18793419, 2008). "What is the relationship between the elevated CXCL12 expression in the bone marrow and development of diabetes in NOD mice?" (PMID 18793419, 2008). "To determine the relationship between CXCL12-mediated dysregulation of T cell and stem cell trafficking and development of diabetes, we treated NOD mice with AMD3100 and monitored progression of the disease." (PMID 18793419, 2008). "The importance of the CXCL12/CXCR4 axis for diabetes therapy has been extensively reviewed." (PMID 40799516, 2025). "Thirdly, multi centre clinical trials are indicated to evaluate the synergistic therapeutic effects of targeted combination strategies, such as PCSK9 + CXCL12, with a particular focus on differential treatment outcomes in patients exhibiting metabolic abnormalities, including diabetes and obesity." (PMID 41283645, 2025). "According to most studies, CXCL12 inhibition inhibits diabetes progression and insulitis, but conflicting reports suggest that adoptive cell transfer may protect against diabetes." (PMID 39070795, 2024). "It is possible that CXCL12 suppression is related to disrupted TGFB signaling in diabetes." (PMID 36307522, 2022). "Moreover, in certain pathological states, like stroke and diabetes, blocking the CXCL12/CXCR4 axis by AMD3100 treatment led to elevated populations of activated macrophages in the ischemic cortex or skin wounds." (PMID 35615089, 2022). "YY1 can reduce the incidence of diabetes by regulating the transcription of the CXCL12 gene." (PMID 33985581, 2021).
diabetes (continued). "The results of this research may help explain the induction of tacrolimus-induced posttransplantation diabetes mellitus via the low expression of muscle genes including Tpm3, Tnnc1, Tnnt1, Tnni3, Hrh3, Apln, S1pr3, and Cxcl12." (PMID 31998808, 2020). "Blockade of CXCL12 inhibits insulitis and diabetes development." (PMID 31507535, 2019). "Indeed, CXCL12 accelerates wound healing in diabetes by recruiting endothelial progenitor cells (EPCs) and through improved angiogenesis." (PMID 26300887, 2015). "However, a note of caution emerges from examinations of the involvement of CXCL12 in the development of diabetes and its complications, as research data indicate that CXCL12 displays effects that range from protective to detrimental." (PMID 26300887, 2015). "Moreover, CXCL12 promotes migration of monocytes and their polarization toward the M2 phenotype, which points to the potential role of CXCL12 in reducing inflammation in diabetes." (PMID 26300887, 2015). "In conclusion, the results of our study suggest that increased spinal levels of CXCL1, CXCL5, CXCL9, or CXCL12 protein in mice after STZ treatment may participate in the development of diabetic neuropathic pain." (PMID 25789329, 2015). "The anti-necrotic effect of CXCL12 could prevent an additional pro-inflammatory burden of β-cells provoked by necrosis and could therefore be used for diabetes treatment." (PMID 26300887, 2015). "RIP-SDF-1 transgenic mice expressing CXCL12 under the control of the insulin promoter, are to some extent protected against streptozotocin-induced diabetes, suggesting that CXCL12 agonists could provide beneficial effects in the treatment of diabetes." (PMID 24988468, 2014). "Based on protection of β-cells against different types of injury, it has been suggested that chemokine CXCL12 or its agonists could provide beneficial effects in diabetes treatment." (PMID 24988468, 2014). "Nevertheless, the elevated CXCL12 expression likely promotes diabetes development." (PMID 18793419, 2008). "Similarly, administration of G-CSF, a cytokine known to induce suppression of CXCL12 transcription, also reduces insulitis and diabetes in NOD mice." (PMID 18793419, 2008). "Moreover, FGF2 and CXCL12 were reduced by diabetes at the protein level (p < 0.001)." (PMID 31001672, 2019). "However, an opposite effect of CXCL12 inhibition was also reported, showing that a population of T cells attracted by CXCL12 protects recipient mice from the capacity of diabetogenic T cells to transfer diabetes." (PMID 31507535, 2019). "In addition, it might promote endothelial cell migration and enhance angiogenesis, the latter effect being supported by reports that CXCL12 promotes angiogenesis in the diabetic retina in rats and oxygen-induced retinopathy in mice." (PMID 28261206, 2017). "Furthermore, the human gene for CXCL12 is located on chromosome 10q11.1, near to the T1D susceptibility locus IDDM10, indicating that CXCL12 gene variants could contribute to diabetes development." (PMID 23555743, 2013). "CXCL12/CXCR4 and CCR4 were also found to be one of the targets for the treatment of diabetic neuropathic pain." (PMID 38617433, 2024). "Studies show that CXCL12 helps protect β-cells from apoptosis and streptozotocin (STZ)-induced diabetes by activating the AKT pathway, which promotes cell survival." (PMID 39070795, 2024). "Diabetes is known to upregulate dipeptidyl peptidase-4 (DDP-4) expression, an enzyme involved in CXCL12 degradation, in the peripheral tissue." (PMID 32485847, 2020). "Our gene expression analysis by RT-qPCR demonstrated that EMP reduced diabetes-induced elevations in the renal expressions of pro-inflammatory cytokine and chemokines TNF-α, MCP-1, CXCL12, and RANTES." (PMID 31168342, 2019). "Treatment of NOD mice with AMD3100, an antagonist for CXCL12's receptor CXCR4, mobilizes T cells and HSC from the bone marrow to the periphery, concomitantly inhibits insulitis and delays the onset of diabetes." (PMID 18793419, 2008).
diabetes (continued). "The group with CXCL13-positive stromal cells had significantly lower HbA1c levels and significantly shorter duration of diabetes compared with CXCL12-negative stromal cells." (PMID 40548381, 2025). "The two studies discussed here were observed under streptozotocin or diet-induced models of diabetes which could explain the conflicting reports of MSC activity and Cxcl12 expression." (PMID 32823583, 2020). "In diabetes, however, CXCL12 in the BM does not decrease following ischemia, leading to an inefficient mobilization of HSPCs." (PMID 32485847, 2020). "CXCL12 also has prognosis potential in non-tumoral processes such as cirrhosis, diabetes, and cardiovascular diseases." (PMID 31507535, 2019). "We found stromal derived factor 1 (SDF1), also referred to as CXCL12, as specifically and strongly downregulated only in skeletal muscles of tumor-bearing mice and not in those undergoing wasting for other reasons (i.e., uremia, diabetes, fasting, or disuse)." (PMID 30984014, 2019). "Indeed, STZ-induced diabetes mice present aberrant SNS signaling in the bone marrow, with impaired expression of CXCL12." (PMID 27406064, 2016). "Conversely, because EA16 mice do not develop diabetes despite the elevated CXCL12 expression and accumulation of T cells in the bone marrow, the elevated CXCL12 expression alone is insufficient to initiate diabetes in the absence of autoreactive T cells." (PMID 18793419, 2008). "Aside from its potential to stimulate β-cell regeneration and prevent apoptosis, capability of CXCL12 to prevent pancreatic β-cells from entering the necrotic cell death by modulating PARP-1 activity, places chemokine CXCL12 in the focal point of developing strategies for diabetes treatment." (PMID 24988468, 2014). "Besides Cxcl12, PARP-1 is also involved in the regulation of several other diabetes-related genes." (PMID 23555743, 2013). "However, one must consider that diabetes is also an inflammation state, and non-specific inflammatory parameters like MIF or CXCL12 can be elevated in patients with IHD or without it." (PMID 35663309, 2022).